SPARC (secreted protein acidic and cysteine rich)
Diseases named in the same sentence as SPARC in open-access papers (continued):
Sharing a sentence is not in itself a finding about the gene and the disease.
gastric cancer (continued). "Increased SPARC expression is linked to advanced gastric cancer, although the expression of SOD2 (Mn-SOD; manganese superoxide dismutase) was significantly enhanced in cancer tissues compared with normal mucosa, and the Mn-SOD ratio was proposed as an independent prognostic parameter." (PMID 18827816, 2008). "In the patients examined here, higher SPARC expression was significantly associated with tumour progression (lymph node metastasis, lymphatic and perineural invasion) and the advanced stages of gastric cancer." (PMID 15558074, 2004). "Maeng found that SPARC is highly expressed in reactive stroma associated with invasive differentiated adenocarcinomas and that it may serve as a useful clinical diagnostic marker for stomach cancer." (PMID 20525171, 2010). "Therefore, the regulation of Bcl-2 and Bax expression may be a key mechanism underlying SPARC induction of apoptosis in gastric cancer cells." (PMID 20525171, 2010). "In gastric cancer, the recombinant SPARC protein markedly influenced 5‐FU chemosensitivity in gastric cancer cells via the modulation of epithelial–mesenchymal transition and apoptosis." (PMID 40415238, 2025). "By analyzing gene expression patterns through single-cell RNA sequencing, we found that several key genes, including SPARC, THBS2, COL1A1, and INHBA, are linked to poor prognosis in gastric cancer." (PMID 40075643, 2025). "In a previous study, we identified six key CAF markers: collagen types COL3A1, COL1A2, COL1A1, COL5A1, and FN1, and SPARC as the pivotal poor prognostic markers in gastric cancer." (PMID 38562556, 2024). "Microarray-based bioinformatics studies revealed increased expression of CAF markers Fibronectin 1 (FN1), Serine proteinase inhibitor 1 (SERPINE1), and secreted protein acidic and cystine-rich (SPARC) genes in gastric cancer patients with low survival." (PMID 38562556, 2024). "Ma and colleagues suggest that SPARC secreted by gastric CAFs is conversely related to the stemness of gastric cancer cells." (PMID 38562556, 2024). "The relationship between stromal-cell-derived SPARC and its clinicopathologic significance was reported in human gastric cancer tissue." (PMID 37509139, 2023). "Subsequently, clinical studies have found that SPARC is a possible marker for diagnosing and prognosticating gastric cancer and an important factor regulating various signaling pathways." (PMID 37577749, 2023). "Clinical data showed that the proficiency of SPARC was significantly reduced in a group of patients with gastric cancer after treatment." (PMID 37577749, 2023). "Genome-scale analysis reveals that SPARC is a marker for the diagnosis and prognosis of gastric cancer." (PMID 37577749, 2023). "A meta-analysis was performed to elucidate that SPARC was a prospective clinical predictor of survival in gastric cancer patients." (PMID 37577749, 2023). "The impact of SPARC on the proliferation and migration of gastric cancer cells was induced by regulating developmental factor arrival." (PMID 37577749, 2023). "Previous research has shown that SPARC methylation occurs at a high rate in gastric cancer tissues and that promoter DNA methylation can inhibit SPARC expression in gastric cancer cells." (PMID 35211625, 2022). "We identified ECM components COL1A1, COL1A2, COL3A1, COL5A1, FN1, and SPARC as the pivotal CAF markers in gastric cancer, which were separately reported as biomarkers of gastric cancer in different studies." (PMID 35739492, 2022). "In this study, we identified the six key CAF markers namely COL1A1, COL1A2, COL3A1, COL5A1, FN1, and SPARC in gastric cancer that can be used as predictors of CAF infiltration and prognostic biomarkers in gastric cancer." (PMID 35739492, 2022). "Our study revealed the COL1A1, COL1A2, COL3A1, COL5A1, FN1, and SPARC as the key CAF markers in gastric cancer." (PMID 35739492, 2022).
gastric cancer (continued). "Previous several studies reported that SPARC expression was distinctly increased in gastric cancer, and its knockdown suppressed the metastasis and EMT progress of GC cells." (PMID 35466319, 2022). "In a stably transfected gastric cancer cell line, SPARC overexpression inhibited the expression of VEGF and MMP-7 and angiogenesis in vitro." (PMID 34209679, 2021). "IHC analysis of human gastric cancer demonstrated that SPARC protein expression was found predominantly in stroma surrounding gastric cancer cells, and SPARC expression was negatively correlated with VEGF expression and MVD." (PMID 34209679, 2021). "Macrophage-derived SPARC reduced the ability of gastric cancer cells to migrate and proliferate in vitro and tumor growth in vivo." (PMID 34209679, 2021). "In gastric cancer, the main sources of SPARC are M2-like TAMs, defined as CD163+ and stabilin-1+ cells, and fibroblasts." (PMID 34209679, 2021). "Previous research results of our research group also found that SPARC is an important tumour suppressor component in gastric cancer 16-18." (PMID 32226513, 2020). "This study shows that macrophages are an important source of the SPARC and that SPARC overexpression in M2 can reduce M2-mediated promoting proliferation, migration and anti-apoptotic effects in gastric cancer." (PMID 32226513, 2020). "To demonstrate the effects of SPARC on the M2-mediated proliferation of gastric cancer, we performed a transwell migration assay." (PMID 32226513, 2020). "The SGC-7901 gastric cancer cells treated with SPARC-treated M2 medium showed an increased apoptosis level at the early stages." (PMID 32226513, 2020). "The two assays illustrated that SPARC overexpression in M2 can reduce M2-mediated proliferation of gastric cancer." (PMID 32226513, 2020). "Secreted protein acidic and rich in cysteine (SPARC) is an important anti-tumour component in the microenvironment of gastric cancer." (PMID 32226513, 2020). "The expression level of SPARC in gastric cancer cells is low, and the promoter methylation of the SPARC gene is one of the main reasons for its loss of expression." (PMID 32226513, 2020). "As a tumour suppressor in the microenvironment of gastric cancer, can SPARC regulate the role of M2 in promoting tumours?" (PMID 32226513, 2020). "In summary, we uncovered the prognostic value of COL3A1/FBN1/COL5A2/SPARC-mir-29a-3p-H19 ceRNA network in gastric cancer." (PMID 32742441, 2020). "Many studies have shown that SPARC is an important tumour suppressor in the gastric cancer microenvironment." (PMID 32226513, 2020). "Endogenous SPARC plays a significant role in reducing M2-mediated proliferation, migration and 5-fluorouracil resistance of gastric cancer." (PMID 32226513, 2020). "Compared with the control group, the BGC-823 and MKN-45 gastric cancer cells treated with SPARC-treated M2 medium showed increased late apoptosis and dead levels." (PMID 32226513, 2020). "The three assays illustrate that SPARC overexpression in M2 attenuated M2-mediated proliferation of gastric cancer." (PMID 32226513, 2020). "CCK-8 showed that the growth of gastric cancer cells, which were co-cultured with SPARC overexpression CM, slowed compared with that of the control group (P<0.05)." (PMID 32226513, 2020). "To determine the effects of SPARC overexpression on M2-mediated proliferation of gastric cancer, we performed a CCK-8 assay and a colony formation assay." (PMID 32226513, 2020). "Decreasing the expression of SPARC in GCAFs exerted a favourable effect in the phenotypic alteration of gastric cancer cells towards CSC-like cells." (PMID 31139014, 2019). "In conclusion, SPARC expression in GCAFs is a useful prognostic factor in patients with gastric cancer." (PMID 31139014, 2019). "Multivariable Cox regression analysis demonstrated that GCAF-derived SPARC was an independent predictive factor for OS in gastric cancer (HR = 0.418, P = 0.015)." (PMID 31139014, 2019).
gastric cancer (continued). "Tumour cell-derived SPARC was reported to inhibit cell proliferation, invasion and angiogenesis in gastric cancer." (PMID 31139014, 2019). "Inhibition of SPARC expression in GCAFs facilitated the phenotypic alteration of gastric cancer cells towards CSC-like cells." (PMID 31139014, 2019). "It has been previously shown by filter migration assays, that gastric cancer cells lost most of their invasive capacity when SPARC was knocked-down." (PMID 31554208, 2019). "A meta-analysis including 10 studies that focused on SPARC expression in gastric cancer showed that SPARC overexpression was highly correlated with reduced OS." (PMID 31139014, 2019). "Subsequent apoptosis analysis revealed that SPARC inhibition in GCAFs suppressed late apoptosis and cell death processes in gastric cancer cells." (PMID 31139014, 2019). "5-FU was introduced into the 3D co-culture model to explore the effect of GCAF-derived SPARC on 5-FU resistance in gastric cancer." (PMID 31139014, 2019). "In the present study, to reveal the clinical significance of GCAF-derived SPARC, we used immunohistochemical staining to evaluate the expression level of SPARC in 192 gastric carcinoma samples." (PMID 31139014, 2019). "Specifically, the expression of SPARC is higher in advanced gastric cancer compared to the early stages, and high SPARC expression significantly correlated with lymph node metastasis, lymphatic invasion and perineural invasion." (PMID 29484116, 2018). "SPARC in human gastric cancer tissue was derived from the stromal cells and was mainly produced by cancer-associated fibroblasts." (PMID 29156791, 2017). "Poorly differentiated gastric cancer tissues showed lower positivity of SPARC staining than well and moderately differentiated gastric cancer tissues(P=0.006)." (PMID 29156791, 2017). "This research on SPARC expression in cancer-associated fibroblasts provided new insight into biological and functional studies of SPARC as well as potential clinical treatment of gastric cancer." (PMID 29156791, 2017). "SPARC+/α-SMA+ cells were the most common phenotype in gastric cancer tissues compared with other phenotypes." (PMID 29156791, 2017). "In this study, we used conventional large tissue sections of gastric cancer instead of TMA for staining of SPARC and counting of positive cells since we found that the distribution of SPARC positive cells in the tumor tissues was unequal." (PMID 29156791, 2017). "Increased expression of SPARC protein in gastric cancer tissues has been proven by several independent groups." (PMID 29156791, 2017). "Compared with other locations, gastric cancer tissue in the cardia and the fundus exhibited higher positivity of SPARC staining (P=0.018)." (PMID 29156791, 2017). "Even though previous researches proved that high expression of SPARC gene in gastric cancer samples was correlated with poor patient survival, our study did not reveal any effect of SPARC protein on the overall survival of the patients during our follow-up." (PMID 29156791, 2017). "In conclusion, our data demonstrated that gastric cancer stromal tissue expressed higher positivity of SPARC protein." (PMID 29156791, 2017). "Lower positivity of SPARC was found in the gastric cancer patients with stage I than those with middle and late stages (II+III+IV) according to the TNM classification (P=0.034)." (PMID 29156791, 2017). "As the depth of tumor invasion and the number of metastatic lymph nodes increased, more SPARC positive cells in the gastric cancer tissue were found." (PMID 29156791, 2017). "Significant up-regulation of the SPARC gene in gastric cancer tissue was first revealed by oligonucleotide microarray technology in 2002." (PMID 29156791, 2017). "Poorly differentiated gastric cancer revealed lower positivity of SPARC staining than well and moderately differentiated gastric cancers." (PMID 29156791, 2017).
gastric cancer (continued). "In this study, fewer SPARC positive cells were observed in the signet ring cell carcinoma and mucinous adenocarcinoma tissues compared with other pathohistological types of gastric cancer." (PMID 29156791, 2017). "Confocal laser fluorescent microscopy was used to reveal the cellular source of SPARC protein in the gastric cancer tissues." (PMID 29156791, 2017). "Increased SPARC expression in gastric cancer tissue was suggestive of a shorter cumulative survival in the patients with gastric adenocarcinoma, though this difference was not statistically significant(P>0.05)." (PMID 29156791, 2017). "Similar to the previous investigation, in this study abundant SPARC was observed in human fibroblast cell line instead of gastric cancer cells." (PMID 29156791, 2017). "In malignant ovarian, colorectal and gastric cancers, SPARC was mainly derived from tumor stromal cells." (PMID 29156791, 2017). "The granulation tissue in gastric cancer samples showed dense and diffuse staining of SPARC protein." (PMID 29156791, 2017). "In this study, we observed that SPARC protein was solely expressed by the stromal cells of gastric cancer tissue instead of cancer cells." (PMID 29156791, 2017). "We aimed to investigate the cellular source of secreted protein acidic and rich in cysteine (SPARC) in gastric cancer tissues and the relationship between SPARC expression and its prognostic significance." (PMID 29156791, 2017). "Western blotting and immunofluorescence staining were applied for verifying the endogenous expression of SPARC in human cell lines of gastric cancer and fibroblast." (PMID 29156791, 2017). "The prognostic role of Secreted Protein Acidic and Rich in Cysteine (SPARC) in gastric cancer (GC) remains controversial." (PMID 28053291, 2016). "In this study, we detected the expression of KAP1, TIMP1, STC2, TLN2, SRPX2, integrin beta 1 (ITGB1) and SPARC mRNAs in peripheral blood samples from pre-operative gastric cancer patients, patients with recurrence, and healthy volunteers." (PMID 23548070, 2013). "In this study, we detected the expression levels of KAP1, TIMP1, STC2, TLN2, SRPX2 and SPARC mRNAs in peripheral blood samples from pre-operative gastric cancer patients, those with recurrence, and in healthy volunteers." (PMID 23548070, 2013). "High SPARC expression in primary tumors, including gastric cancer, correlates with metastasis and poor prognosis." (PMID 22321704, 2012). "Earlier studies by our group have shown that SPARC, CLIC1, SLPI, CXCL1, CXCL8, and CXCR2 are highly expressed and associated with advanced stages and poor prognosis of gastric cancer." (PMID 22479608, 2012). "In order to investigate the role of SPARC in gastric cancer, we first tested the expression of SPARC in seven cell lines of gastric cancer." (PMID 22957090, 2012). "To determine the role of SPARC in the growth and angiogenesis of gastric cancer, we established the BGC-SP clone which was stably transfected with a SPARC cDNA vector, and the HGC-sh clone which was stably transfected with a shRNA vector targeting SPARC mRNA." (PMID 22957090, 2012). "In this study, we aimed to determine the effect of SPARC expression in gastric cancer cells on proliferation and angiogenesis in vitro and in vivo." (PMID 22957090, 2012). "Response to docetaxel, a taxane drug that inhibits mitotic spindle assembly, is reportedly impacted by the amount of SPARC protein expression in gastric cancer." (PMID 22929309, 2012). "SPARC expresses in normal gastric epithelial cells, gastric cancer cells, and the stromal cells surrounding gastric cancer at a lower level." (PMID 22957090, 2012). "SPARC suppresses angiogenesis of gastric cancer by down-regulating the expression of VEGF and MMP-7." (PMID 22957090, 2012). "Recent immunohistochemistry study found that SPARC expression was negatively correlated with the expression of VEGF and MVD in gastric cancer tissues, and SPARC expression decreased in gastric cancer with higher grade of malignancy." (PMID 22957090, 2012).
gastric cancer (continued). "Studies have unraveled many aberrantly expressed genes in gastric cancer including BMI1, COX-2, HER3, RKIP and STAT3, SPARC and HER2, which make risk assessment of gastric cancer patients more accurately." (PMID 21933426, 2011). "In conclusion, our current data suggested that SPARC played important roles in apoptosis and metastasis of gastric cancer." (PMID 20525171, 2010). "MGC803 and HGC27 gastric cancer cells transfected with SPARC siRNA survived at decreased rates relative to matched cells transfected with a non-targeting control siRNA." (PMID 20525171, 2010). "Our data showed that downregulating of SPARC inhibits invasion and growth of human gastric cancer cells." (PMID 20525171, 2010). "Because SPARC was found to be overexpressed in human gastric cancer tissue, we therefore to explore the expression of SPARC in gastric cancer lines and the carcinogenic mechanisms." (PMID 20525171, 2010). "Through expression analysis of a panel of gastric cancer cell lines, we showed that SPARC is also overexpressed in sevel human gastric cancer cell lines." (PMID 20525171, 2010). "MGC803 and HGC 27 gastric cancer cell lines expressing high level of SPARC were transiently transfected with SPARC-specific small interfering RNAs and subsequently evaluated for effects on invasion and proliferation." (PMID 20525171, 2010). "SPARC protein and mRNA expressed significantly higher in gastric cancer tissues compared to normal tissues." (PMID 20525171, 2010). "Among them, SPARC was the most highly expressed gene in the diffuse type and the second most highly expressed in the intestinal type of gastric cancer." (PMID 15558074, 2004). "Using cDNA microarry, we identified a highly expressed gene for gastric cancer, Secreted Protein, Acidic and Rich in Cysteine (SPARC), also designated as osteonectin and BM40." (PMID 15558074, 2004). "In the gastric cancer patients included in this study, the SPARC expression was similar to that of oesophageal cancer, detected mainly in the gastric cancer cells, and less intensively in the stroma cells." (PMID 15558074, 2004). "We found that SPARC expression was significantly higher in the advanced stage of gastric cancer in comparison to the early stage, indicating SPARC potential as a marker for the more advanced forms of gastric cancer." (PMID 15558074, 2004). "In this study, SPARC was identified, by cDNA microarray, as one of the most overexpressed genes in more than 60% of the gastric cancer patients included in this study." (PMID 15558074, 2004). "Our finding was similar to that in one report on gastric cancer study, but different from another report, where SPARC stained only the stroma cells in gastric cancer tissues." (PMID 15558074, 2004). "Additionally, SPARC overexpression in implanted gastric cancer cells interfered with the epithelial-mesenchymal transition and decreased cell viability and migratory ability; further, SPARC overexpression also inhibited VEGF expression." (PMID 38928185, 2024). "These outcomes implicate that SPARC may induce apoptosis in gastric cancer through the activation of the PARP/caspase-3 pathway." (PMID 39336798, 2024). "The tumor suppressor gene, SPARC gene, is underexpressed in gastric cancer cell family." (PMID 37577749, 2023). "In patients with stage II/III gastric cancer, high levels of SPARC gene expression may be a valuable prognostic factor." (PMID 37577749, 2023). "SPARC brings new targets and therapies to treat gastric cancer." (PMID 37577749, 2023). "The expression of SPARC was negatively correlated with differentiation, Lauren classification, lymph node metastasis, and clinical stage, while lymph node metastasis was an independent prognostic factor for patients with gastric cancer." (PMID 35211625, 2022). "Studies have found that SPARC is mainly expressed in mesenchymal cells in gastric cancer tissue." (PMID 35211625, 2022).